KLF8 (KLF transcription factor 8)
Diseases named in the same sentence as KLF8 in open-access papers (continued):
Sharing a sentence is not in itself a finding about the gene and the disease.
tumor (continued). "To determine to what extent the KLF8-miR141-EGFR axis affects tumor progression in the breast, we orthotopically injected the 231-K8ikd cells or the 231-K8ikd-miR141 cells into the mammary fat pad and then measured the tumor growth and invasion." (PMID 26025929, 2015). "High expression of KLF8 was also associated with poor PDAC prognosis and higher tumor stages." (PMID 37239940, 2023). "In addition, in vivo findings verified that NEDD4 regulates the KLF8/miR-132/NRF2 axis by accelerating tumor growth and lung metastasis." (PMID 35031788, 2022). "KLF6 is a tumor suppressor, while KLF8 functions as an oncogene in CRC." (PMID 32523679, 2020). "Chi‐square analysis indicated that high KLF8 expression significantly correlated with larger tumour diameter (P < 0.001), advanced T stage (P = 0.003) and N stage (P < 0.001), suggesting that KLF8 may promote tumour progression." (PMID 31124603, 2019). "Similarly, the indicators for tumor development and progression, MMP-2 and MMP-9 were also inhibited by KLF8 silencing, which just proved the alterations of tumor malignancies at molecular level." (PMID 31827393, 2019). "In conclusion, this present study develops a novel insight that the TSCC tumor progression may be regulated by DANCR/miR-135a-5p/KLF8 axis." (PMID 31827393, 2019). "As expected, knockdown of KLF8 (I) significantly slowed down the tumor growth (compare I with U)." (PMID 26993780, 2016). "Histological analyses revealed that the dramatic inhibition of the tumor invasion into the surrounding tissues by knockdown of KLF8 (compare I with U) was also well prevented by overexpression of CXCR4, but not its dN20 mutant (compare I+CXCR4 or I+dN20 with I)." (PMID 26993780, 2016). "To see whether EGFR expression in the same tissue microarray is correlated with KLF8 expression and the tumor invasive potential, we performed an immunohistochemical (IHC) staining for EGFR expression." (PMID 26025929, 2015). "As demonstrated for some other non-glial cancer entities, KLF8-knockdown by shRNA in U87-MG cells confirmed its functional relevance, leading to an almost complete loss of tumor cell proliferation." (PMID 22276196, 2012). "Enhanced expression of KLF8 has been shown in several types of non-CNS tumor cells and primary tumor tissues where it has been associated with malignancy." (PMID 22276196, 2012). "However, the molecular mechanism by which KLF8 affects FHL2-mediated tumor proliferation, EMT and metastasis remains unknown." (PMID 26320172, 2015). "In solid tumors, KLF8, on binding to the upstream region of the MDR1, promotes translational activity in the tumour microenvironment under hypoxic conditions and thus, inhibiting apoptosis and augmenting the rate of efflux of the chemotherapeutic agent." (PMID 40176914, 2025). "Two GRNs, albeit comprising a smaller number of tumor cells, showed high activity for the TCF7L2 regulon (along with KLF8, FOXK1, FOXP2, BACH1) (labeled TCF7L2+) and CTCF (along with MAFG and NR1H) (labeled CTCF+) respectively." (PMID 38645034, 2024). "Two GRNs, albeit comprising a smaller number of tumor cells, showed high activity for the TCF7L2 regulon (along with KLF8, FOXK1, FOXP2, and BACH1) (labeled TCF7L2+) and CTCF (along with MAFG and NR1H) (labeled CTCF+), respectively." (PMID 38968122, 2024). "KLF8 plays the exact biological role as lithium chloride that activates the canonical WNT signaling and maintains the stem cell-like characteristics of tumor cells, thus achieving strong tumorigenicity." (PMID 36761967, 2023). "Knockdown of KLF8 in SUM159 cell significantly reduced bioluminescent signal, tumor volume and tumor weight compared to controls." (PMID 37152043, 2023). "However, the role of KLF8 in CSCs and tumor initiation remains unknown." (PMID 37152043, 2023). "Compared to para-tumor specimens, the mRNA levels of KLF5, KLF7, KLF8, and KLF13 were elevated, whereas those of KLF4, KLF6, and KLF10 were reduced in HCC specimens." (PMID 37554278, 2023).
tumor (continued). "KLF8 had decreased activity in GBM, LIHC and KIRC, which is consistent with its role in suppressing cell apoptosis during tumor progression." (PMID 36243974, 2022). "Expression of SS-induced genes, such as Early growth response 1 (Egr1), Activator protein 1 (Ap1), Epithelial cell adhesion molecule (Epcam), and Kruppel-like factor 8 (Klf8), were the highest in the circulating GFP+ tumor cells." (PMID 30651129, 2019). "In vivo, the tumor growth and the expression of matrix metalloproteinase (MMP)-2/9 and KLF8 were also blocked by DANCR inhibition." (PMID 31827393, 2019). "In the present study, we examined the expression of and relationship between KLF8 and VEGF in the tumor tissues of HCC patients." (PMID 30479372, 2018). "The tumor-centered blood vessel number (BVN) was counted, and the BVNs of the KLF8 overexpression group and control group were 61.67±6.51 and 30.00±3.61, respectively." (PMID 30479372, 2018). "The tumor-suppressive role of miRNA-1236-3p is demonstrated by its ability to reduce cell proliferation and induce cell cycle arrest in HOS and U-2OS cells at the G0/G1 phase through the down-regulation of Krüppel-like factor 8 (KLF8)." (PMID 39419925, 2025). "Furthermore, the cooperation between FAK and Krüppel-like factor 8 (KLF8) enhances VEGFA expression, contributing to angiogenesis and tumor growth." (PMID 38338842, 2024). "Mechanically, KLF8 inhibits the transcription of miR‐429 by binding to its promoter region, thus directly activating the sex‐determining region Y‐box 2 (SOX2) which can promote tumour cell stemness, and finally promote the CD133‐positive CSCs‐like phenotype." (PMID 38546623, 2024). "Interestingly, KLFs can exert opposite effects in regulating the same pathways and initiate different cell responses, as some of them can function as tumor suppressors (KLF2, KLF8) and some as oncogenes (KLF7, KLF9)." (PMID 37239940, 2023). "Additionally, Krüppel-like factor 8 (KLF8) cooperates with FAK to promote VEGFA expression consequent to angiogenesis and tumor growth." (PMID 35163650, 2022). "Overall, these in vivo results show that DANCR may activate the expression of KLF8 and MMPs to affect TSCC tumor growth." (PMID 31827393, 2019). "First, we did not perform animal studies to examine the effects of KLF8 on tumour progression and metastases in vivo, and thus further in vivo studies are needed to validate our findings." (PMID 31124603, 2019). "The KLF8 stable-transfectant group showed significantly increased proliferation rates and tumor vessel density than those in the vector group, whereas knockdown of FHL2 inhibited the growth rate and tumor vessel density in the KLF8-overexpressing group." (PMID 26320172, 2015). "Similarly, knockdown of DANCR inhibited tumor growth and KLF8 expression in vivo, suggesting that DANCR may play an essential role via miR-135a-5p/KLF8 axis." (PMID 34722539, 2021). "Also, KLF8 is known for its ability of inducing EMT and drug resistance in tumor progression." (PMID 32411796, 2020). "Moreover, recent findings support the importance of KLF8 in malignant cell transformation and tumor growth of several different non-CNS tumors." (PMID 22276196, 2012). "Interestingly, the cell cycle regulating genes associated with tumor growth such as cyclin D1 and USP44 are regulated by KLF8 in T80 but not in MCF10A, whereas the EMT and metastasis associated genes such as E-cadherin, MMPs, and EPSTI1 are regulated by KLF8 in MCF10A but not in T80." (PMID 25485290, 2014). "In the overall cohort, significant differences between patients with negative and tumor-indicative PSMA scans were found for 2/8 (25%) of the analyzed meth-ctDNA markers (CHST11 (p = 0.007), KLF8 (p = 0.026)) and PSA (p < 0.001), with the highest AUC for PSA (AUC 0.77, CI = [0.683; 0.857])." (PMID 40001235, 2025).
infection (2 papers, 2013 to 2014). The state of being infected such as from the introduction of a foreign agent such as serum, vaccine, antigenic substance or organism. "Therefore, the present study investigated the effect of KLF8-siRNA lentiviral infection on Saos-2 cell cycle arrest and its association with Saos-2 cell growth inhibition." (PMID 24604387, 2014). "In this study, GFP containing lentivirus mediated infection of KLF8 siRNA in CAL 27 cells was performed." (PMID 23722127, 2013).
CNS tumors (1 paper, 2012). "Since KLF8 has been linked to proliferative activity of non-CNS tumors, we additionally stained consecutive sections with the widely used proliferative marker Ki67." (PMID 22276196, 2012). "On the other hand, these highly aggressive non-CNS tumors have mesenchymal cell origin and KLF8 has also been shown to trigger epithelial-to-mesenchymal transition, which might in part explain overexpression of KLF8 in these tumors." (PMID 22276196, 2012).
KLF8 also shares sentences with these, for which no sentence is quoted: pancreatic cancer (2 papers); cardiac disease (1); coronary atherosclerosis (1); diabetes (1); invasive ductal carcinoma (1); invasive lobular carcinoma (1); ischemic heart disease (1); lung adenocarcinoma (1); meningioma (1); metastatic disease (1); sarcoma (1); tongue squamous cell carcinoma (1).